IL6 (interleukin 6)
Diseases named in the same sentence as IL6 in open-access papers (continued):
Sharing a sentence is not in itself a finding about the gene and the disease.
Cognitive impairment (567 papers, 2009 to 2026). Abnormal cognition is characterized by deficits in thinking, reasoning, or remembering. "In summary, this study demonstrates that CP induces cognitive deficits associated with increased hippocampal levels of inflammatory markers (IL-1β, IL-6, NF-κB, and TNF-α) and apoptotic markers (caspase-3 and BAX)." (PMID 41256255, 2025). "In general, there seems to be a tendency towards higher IL-β and IL-6 being associated with cognitive impairment during and after ChT." (PMID 41228315, 2025). "While IL-6 was the most frequently elevated, only one study reported an association with cognitive impairment." (PMID 41155372, 2025). "The association between IL-6 and cognitive impairment is supported by animal models, wherein elevated IL-6 levels have been linked to poorer cognitive outcomes." (PMID 40007697, 2025). "IL6 is a mediator of inflammation whose signaling has been associated with cognitive impairment in AD." (PMID 40333680, 2025). "Several studies have observed that certain proteins in plasma, such as IL-6, are highly associated with cognitive impairment and dementia risk." (PMID 41009474, 2025). "The effect of these inflammatory biomarkers is associated with cognitive dysfunction, and the increase in IL6 levels is a predictor of advanced cognitive impairment." (PMID 40699836, 2025). "An increase of one unit log-transformed IL-6 levels was significantly associated with 35 % higher odds of cognitive impairment (OR = 1.35 [1.13, 1.60], pFDR-value<0.001) and 29 % higher odds of TMT-B ≥ 90 s (OR = 1.29 [1.07, 1.56], pFDR-value = 0.011)." (PMID 40606939, 2025). "Key findings indicate that elevated levels of inflammatory markers such as IL‐6, IL‐1β, and sTNFRs are linked to cognitive impairment and neurodegeneration, while the role of IL‐10 and IL‐8 present varying associations based on demographic factors." (PMID 40709483, 2025). "In elderly hospitalized patients, delirium onset was significantly associated with cytokines IL-6 and Il-8, even after adjusting for confounders such as age, infection, and baseline cognitive impairment." (PMID 39860413, 2025). "Lastly, while several studies have reported association between higher IL-6 in the blood and poorer cognitive performance in PWH, in the CSF, lower levels of IL-6 have been consistently associated with cognitive impairment." (PMID 40573339, 2025). "Chronic inflammation serves as a central pathogenic driver in cerebrovascular and cognitive disorders, orchestrated by pro-inflammatory cytokines including interleukin-6 (IL-6), tumor necrosis factor-α (TNF-α), and interleukin-1β (IL-1β)." (PMID 40918522, 2025). "Elevated CRP and IL-6 levels are consistently associated with stress-perception phenotypes, cognitive impairment, and progression to dementia in vulnerable individuals, particularly when combined with pain and emotional stress." (PMID 41373439, 2025). "Higher levels of IL-6 in older adults have been cross-sectionally and longitudinally associated with cortical thinning, cognitive impairment, and increased dementia risk." (PMID 41465427, 2025). "Cytokines, including TNF, IL-1 ß, and IL-6, have been described to affect the synaptic plasticity and neurogenesis which are implicated in learning and cognitive impairment." (PMID 38150137, 2024). "Two genomic variants of IL6 gene are most frequently associated with mental and cognitive disorders: rs1800795 and rs1800796." (PMID 38646100, 2024). "Recently, a prospective study investigated the impact of IL‐6 on cognitive performance and showed elevated IL‐6 levels were independently associated with cognitive impairment in patients with ischemic stroke and transient ischemic attack." (PMID 38376025, 2024). "The proinflammatory cytokine IL6 usually increases with age and has been associated with cognitive impairments." (PMID 38352704, 2024).
Cognitive impairment (continued). "For example, associations between cognitive deficits and elevated triacylglycerol and glucose or higher cytokine IL6 have already been found." (PMID 37836395, 2023). "Potentially, IL6 rs1800795 influences IL6 expression, which can be further associated with cognitive impairment." (PMID 38275640, 2023). "IL-6 has been shown to play a significant role in the pathogenesis of neurodegenerative diseases and has been linked to cognitive impairment in Alzheimer ́s disease." (PMID 37507580, 2023). "A few studies also identified imbalances in TNF-α, IL-1, and IL-6 as being implicated in mood and cognitive impairments." (PMID 38138916, 2023). "First, sarcopenia and cognitive disorders share similar risk factors as follows: inflammation, characterized by interleukin-6 (IL-6) and tumor necrosis factor-α; oxidative stress; hormonal changes; and malnutrition." (PMID 36837864, 2023). "As an essential pro-inflammatory cytokine, enhanced IL-6 levels are associated with surgical trauma and can cause cognitive deficits." (PMID 38082225, 2023). "Our results suggest that higher levels of IL-6 were associated with cognitive impairment in an older adult population of Southern Italy." (PMID 36915478, 2023). "IL-6 has also been associated with fatigue and cognitive impairment in a cohort of PASC patients who had mild acute infection." (PMID 37313412, 2023). "In previous studies, elevated IL-6 levels were usually associated with more severe symptoms and cognitive deficits in schizophrenic patients." (PMID 37370004, 2023). "Dysregulation of IL-6 is associated with various cognitive dysfunction, and individuals with high levels of IL-6 in the blood are at a higher risk of cognitive impairment than individuals with low Levels of IL-6." (PMID 36466655, 2022). "Our results together with previous evidence can serve as a pre-clinical justification for IL-6 modulation as a strategy to alleviate delirium associated cognitive impairment." (PMID 36160165, 2022). "High level of NO in the brain was associated with elevated levels of interleukin-6 and tumor necrosis factor-α, both of which can contribute to cognitive impairment through tau phosphorylation." (PMID 35911235, 2022). "IL-6, also known as a proinflammatory factor, can activate microglia and astrocytes and cause neuronal damage and cognitive impairment by inducing the production of neurotoxic transmitters." (PMID 34630618, 2021). "Proinflammatory cytokines, such as TNF-α and IL-6, are associated with neuroinflammation and lead to cognitive impairment following surgery under cbupivacine anesthesia." (PMID 33179100, 2021). "In our study, male sex, severe cognitive impairment, underlying heart disease, anemia, and elevated plasma levels of IL-6 were independently associated with greater mortality during hospitalization." (PMID 34682421, 2021). "Although this suggests an association between IL-6 and AD pathogenesis, a causal link between IL-6, cognitive deficits, and peripheral metabolic dysregulation in AD remains to be established." (PMID 33911072, 2021). "After adjustment for age and sex, PD-cognitive deficit was positively associated with plasma EV pro-IL-1β, IL-6, TNF-α, and IL-10 levels and negatively with the TGF-β1 level." (PMID 33803292, 2021). "Although regular aerobic exercise causes reductions in serum IL-6 levels in older healthy adults and individuals with mild cognitive impairment, the effects of exercise on IL-6 level in AD remain poorly studied." (PMID 34445419, 2021). "First, we found that sevoflurane increased amounts of phosphorylated Tau (pTau) (Tau-PS202/PT205) and IL-6, and induced mitochondrial dysfunction, synaptic loss and cognitive impairment in young WT mice." (PMID 34589883, 2020).
Cognitive impairment (continued). "They examined the cross-sectional and longitudinal associations between baseline-measured IL-6, IL-10, and tumor necrosis factor (TNFα) levels in the blood and the ratio of IL-6/IL-10 with cognitive test performance and mild cognitive impairment." (PMID 32455758, 2020). "A cohort study reported that individuals with elevated IL-6 level are at a greater risk of cognitive impairment." (PMID 32765394, 2020). "In the IL-6 KO mice, sevoflurane caused a lesser degree of mitochondrial dysfunction, synaptic loss, and cognitive impairment, but still increased Tau phosphorylation in hippocampi of the mice." (PMID 34589883, 2020). "Our previous studies showed that anesthetic sevoflurane induced Tau phosphorylation, IL-6 elevation, mitochondrial dysfunction and synaptic loss in brain tissues of neonatal mice, as well as cognitive impairment in the mice." (PMID 34589883, 2020). "The findings in the present studies suggest that Tau phosphorylation causes IL-6 elevation, which induces mitochondrial dysfunction, leading to synaptic loss and cognitive impairment in the young mice following sevoflurane anesthesia." (PMID 34589883, 2020). "Chronic peripheral elevation of interleukin 6 (IL-6) in humans is associated with cognitive deficits." (PMID 31129771, 2019). "Its activation eventually increases level of pro-inflammatory cytokines in brain, such as TNF-α and IL-6, which subsequently cause cognitive impairment." (PMID 31759387, 2019). "Inflammation and high levels of IL-6 are associated with both the severity of schizophrenia and the cognitive impairment suffered throughout the disease." (PMID 30678202, 2019). "New data point, in particular, to the association between the levels of interleukin 6 (IL-6) and modifications of the offspring’s salience network and subsequent cognitive impairments." (PMID 30344483, 2018). "IL-6 is known to have central actions, is elevated in the elderly, and is associated with cognitive impairments and decline." (PMID 28081177, 2017). "Specifically, IL-6 has been reported to be associated with learning and memory impairment in animals, cognitive dysfunction, mild cognitive impairment, and delirium in patients." (PMID 28848542, 2017). "Pro-inflammatory cytokines, particularly IL-1β, TNF-α and IL-6, are associated with cognitive impairment." (PMID 29238302, 2017). "It was also reported that increased IL-6 brain showed that severe cognitive impairments and behavioral deficits with neuronal loss." (PMID 29052076, 2017). "It has been reported that pro-inflammatory cytokines, such as TNF-α, IL-1β, and IL-6, are associated with cognitive impairment." (PMID 28086911, 2017). "In line with other studies, cytokine levels (IL-6) were strongly associated with self-perceived cognitive impairment." (PMID 27701469, 2016). "Association of IL-6 concentrations with severity of self-perceived cognitive impairment (FACT-Cog) and the cognitive domains of HeadminderTM." (PMID 27701469, 2016). "Although we were unable to establish the genetic associations with cognitive impairment, we have observed that patients manifesting higher levels of IL-6 were associated with greater severity of self-perceived cognitive impairment." (PMID 27701469, 2016). "Higher plasma concentrations of IL-6 were associated with greater severity of self-perceived cognitive impairment (p = 0.001)." (PMID 27701469, 2016). "At this stage, it is believed that the main factors causing cognitive impairment effects are decreased ACh content and increased P-tau protein and IL-6 in CSF." (PMID 26271247, 2015). "Higher interleukin-6 (IL-6) levels were associated with cognitive impairments on the domain Executive Functions, whereas higher IL-8 levels were associated with better Memory performance." (PMID 24661373, 2014).
Cognitive impairment (continued). "High level of IL-6 was also associated with several baseline features (including poor functional status, cognitive impairment, emergency admission, and higher comorbidity burden) and intra-hospital mortality." (PMID 25368603, 2014). "Elevated IL-6 levels are also associated with cognitive impairment in AD patients." (PMID 41373742, 2025). "In AD, IL6 signaling has been linked with cognitive impairment and metabolic alterations." (PMID 39670387, 2025). "Specifically, an early increase in the levels of pro-inflammatory cytokines TNF-α, IL-6 and IL-1β was generally observed across studies (measured in the hippocampus and/or plasma), with these increases being associated with the cognitive impairments observed in the animals." (PMID 41155372, 2025). "Several studies described the association between high IL-6 levels and cognitive impairment." (PMID 40606939, 2025). "Strong evidence suggests that elevated maternal levels of IL-6 are associated with changes in the connectivity of the amygdala and fronto-limbic white matter in newborns, which in turn are linked to working memory and cognitive impairment later in life." (PMID 40869088, 2025). "Notably, the pro-inflammatory cytokine interleukin-6 (IL-6) has been associated with cognitive impairments in individuals with substance use disorders." (PMID 40565488, 2025). "High concentrations of IL-6 may therefore be an important factor promoting the development of cognitive impairments and may be linked to their prevalence." (PMID 40305179, 2025). "This study found that in the hippocampus of mice with cognitive impairment caused by sevoflurane, the expression levels of IL‐6 decreased, along with a reduction in the phosphorylation level of ERM proteins and a slowing down of the protein phosphorylation process." (PMID 38698533, 2024). "P. gingivalis periodontal infection may cause cognitive impairment or neuroinflammation via the release of the pro-inflammatory cytokines IL-6, TNF-α, and IL-1β." (PMID 38764065, 2024). "IL-6, a key player in the early stages of amyloid plaque formation in the brain of patients with AD, has also been linked to tau phosphorylation, synapse loss, and cognitive impairment in mouse models of AD." (PMID 39286235, 2024). "Also, basic research suggests that inflammatory markers and hormonal pathways (interleukin-6, C-reactive protein, myokines, and serum testosterone) play a role in the association between sarcopenia and cognitive impairment." (PMID 38613024, 2024). "In conclusion, our study shows that higher IL-6 serum levels are associated with global cognitive impairment and worse executive functioning in a wide sample of older adults in South Italy, suggesting that neuroinflammation mediated by IL-6 plays a role in cognitive decline." (PMID 36915478, 2023). "Several meta-analyses of prospective studies have demonstrated that peripheral IL-6 expression is associated with cognitive decline in adults without dementia, which has been identified as a blood marker of cognitive impairment and the severity of cognitive dysfunction." (PMID 37254162, 2023). "To investigate whether inflammation is associated with cognitive impairment, we measured hippocampal expression of cytokines IL-1β, IL-6, and TNF-α." (PMID 37091543, 2023). "Moreover, IL6 has been associated with cognitive impairment proportionally, i.e., a high IL6 concentration is linked with a high rate of executive and memory function deficit in elderly participants." (PMID 38275640, 2023). "Innate fat cells and immune cells that have been activated have the potential to produce the proinflammatory cytokine IL-6, which suggests that higher levels of body fat deposition are connected with higher levels of IL-6 production and a higher risk of cognitive impairment." (PMID 36678130, 2023).
Cognitive impairment (continued). "Accumulated epidemiological, clinical, and basic research evidence indicates that inflammatory markers and the hormonal pathway (e.g., interleukin-6, C-reactive protein, myokine, and serum testosterone) are involved in the association between sarcopenia and cognitive impairment." (PMID 37139093, 2023). "Our results corroborate this hypothesis since we observed that in partial correlation analysis, elevated SLEDAI scores and IL-6 levels were associated with cognitive impairments in the same domains." (PMID 38093175, 2023). "However, this hints at an involvement of IL-6 in AD disorders, and a fundamental association between IL-6, cognitive impairments, and peripheral metabolic disorganization in AD continues to be recognized." (PMID 37376007, 2023). "Additionally, systemic maternal inflammation during pregnancy, especially elevated Il-6 levels, have been associated with cognitive impairment and development of psychiatric disease." (PMID 37355708, 2023). "They found that neither baseline levels nor slopes of IL-6 were related to cognitive impairment or hippocampal volumes, but IL-6 variability was positively associated with cognitive impairment and with a greater decrease of grey matter volume of the hippocampus." (PMID 37467176, 2023). "This speculation aligns with one report of human cancer patients, in which increased circulating IL-6 was associated with cognitive impairment." (PMID 36699654, 2022). "Also, increased TNF-α and IL-6 are correlated with high risk of mild cognitive impairment in type 2 diabetes patients." (PMID 35239774, 2022). "Furthermore, to our knowledge, this is the first study to report an association between pro-inflammatory cytokines, IL-6 and TNFα and low vegetable consumption in elderly with mild cognitive impairment." (PMID 35052306, 2022). "Diabetes can increase TNF-α and IL-6 levels, cause the brain’s TJ protein to degrade, aggravate inflammation and leukocyte infiltration, encourage the breakdown of the blood-brain barrier, and ultimately result in cognitive impairment." (PMID 36678547, 2022). "TNF-α and IL-6 are pro-inflammatory cytokines that are associated with cognitive impairment." (PMID 34248475, 2021). "In the multivariate Cox proportional hazard analyses, increased risk of in-hospital mortality was associated with severe cognitive impairment on admission, heart disease morbidity, and increased frequency of abnormalities in selected laboratory parameters, such as low hemoglobin and high IL-6." (PMID 34682421, 2021). "Various studies suggest that cognitive impairment may be associated with the interaction of various cytokines, including IL-6, IL-1β, TNF-α, and microglia." (PMID 34669701, 2021). "Besides, through rigorous regression analysis, the elevated plasma IL-6 level tended to be a risk factor leading to cognitive impairment." (PMID 34869762, 2021). "We tested a hypothesis that the interactions of Tau phosphorylation, IL-6 elevation and mitochondrial dysfunction following sevoflurane treatment caused synaptic loss in young mice, leading to cognitive impairment in the mice." (PMID 34589883, 2020). "The fact that altered virome is strongly correlated with higher circulatory IL6 and microglial activation, the present study may throw important viewpoints for further mechanistic studies into cognitive impairment associated with GWI." (PMID 31640184, 2019). "Furthermore, IL-6 demonstrates consistent associations with frailty and cognitive impairment in older persons." (PMID 30352583, 2018). "Some proinflammatory cytokines, such as IL-1β and IL-6, have been associated with reduced amyloidosis and amelioration of cognitive deficits in APP mouse models, and may contribute to the beneficial effects of FUS in AD." (PMID 30232364, 2018).